PUS1 (pseudouridine synthase 1)
Diseases named in the same sentence as PUS1 in open-access papers (continued):
Sharing a sentence is not in itself a finding about the gene and the disease.
infection (1 paper, 2023). The state of being infected such as from the introduction of a foreign agent such as serum, vaccine, antigenic substance or organism. "Infection of PUS1-LV significantly potentiated viability in a time dependent-manner, promoted migration, enhanced invasion, and increased colony numbers in A498 cells." (PMID 37315299, 2023). "Conversely, infection of PUS1-shRNA-LV resulted in the opposite effects in ACHN cells, including lowered viability at different time points, particularly at 48 h, 72 h and 96 h, down-regulated migration, suppressed invasive capability, and decreased colony numbers." (PMID 37315299, 2023).
PUS1 also shares sentences with these, for which no sentence is quoted: Encephalopathy (2 papers); mitochondrial disease (2); Pearson marrow-pancreas syndrome (2); anaemia (1); autosomal recessive disease (1); benign prostatic hyperplasia (1); cardiomyopathy (1); congenital anemia (1); congenital sideroblastic anemia (1); deafness (1); gastric cancer (1); glioblastoma (1); Hepatitis (1); hereditary thrombocytopenia (1); hypertrophic cardiomyopathy (1); liver failure (1); melanoma (1); MELAS (1); metastatic tumors (1); pancytopaenia (1); prostate adenocarcinoma (1); septic shock (1).